DYNLRB2 (dynein light chain roadblock-type 2)
Description:
Acts as one of several non-catalytic accessory components of the cytoplasmic dynein 1 complex that are thought to be involved in linking dynein to cargos and to adapter proteins that regulate dynein function. Cytoplasmic dynein 1 acts as a motor for the intracellular retrograde motility of vesicles and organelles along microtubules.
Synonyms: DNCL2B; DNLC2B; ROBLD2
Tractability: Small molecule: a structure with a bound ligand is known. PROTAC: ubiquitination databases record sites on it.
Gene: Protein-coding gene on chromosome 16 (80,540,734 to 80,550,811, forward strand). Ensembl gene ENSG00000168589.
Subcellular location: Cytoplasm, cytoskeleton
Pathways (Reactome):
Organelle biogenesis and maintenance: Intraflagellar transport
Gene Ontology:
Molecular function: dynein intermediate chain binding; microtubule motor activity
Biological process: intraciliary retrograde transport; microtubule-based movement; positive regulation of intracellular transport; positive regulation of mitotic cell cycle spindle assembly checkpoint
Cellular component: centrosome; ciliary tip; cilium; cytoplasm; cytoplasmic dynein complex; dynein complex; male germ cell nucleus; cytoskeleton
Genetic constraint (gnomAD): Loss-of-function variants: 14 observed, 13.33 expected, observed/expected ratio (o/e) 1.05, 90% interval 0.69 to 1.62. The upper end of that interval is the gene's LOEUF score, 1.62, which puts it in group 6 of 6, group 1 being the genes least tolerant of losing a copy. Missense variants: 142 observed, 121.46 expected, observed/expected ratio (o/e) 1.17, 90% interval 1.02 to 1.34. Synonymous variants: 53 observed, 39 expected, observed/expected ratio (o/e) 1.36, 90% interval 1.09 to 1.71.
Homologues: Orthologues: chimpanzee DYNLRB2 (99% identical), macaque DYNLRB2 (99% identical), rabbit DYNLRB2 (99% identical), mouse Dynlrb2 (98% identical), pig DYNLRB2 (97% identical), guinea pig DYNLRB2 (96% identical), tropical clawed frog dynlrb2 (96% identical), zebrafish dynlrb2 (86% identical), rat Dynlrb2 (84% identical), Drosophila melanogaster robl (75% identical), dog DYNLRB2 (75% identical), Caenorhabditis elegans dyrb-1 (45% identical). Paralogues in human: DYNLRB1 (77% identical).
Diseases named in the same sentence as DYNLRB2 in open-access papers:
DYNLRB2 is named in the same sentence as 15 diseases in open-access papers, as found by Europe PMC text mining. Sharing a sentence is not in itself a finding about the gene and the disease. The quoted sentences say what the papers report.
atherosclerosis (3 papers, 2019 to 2024). A disease characterized by the build-up of fatty material and calcium deposition in the arterial wall resulting in partial or complete occlusion of the arterial lumen. "However, deprivation of DYNLRB2 has been associated with decreased circulating lipids and mitigated atherosclerosis." (PMID 39273193, 2024). "This implies that DYNLRB2 may exert an influence on lipoprotein metabolism and the progression of atherosclerosis." (PMID 39273193, 2024).
Alzheimer disease (1 paper, 2025). A progressive, neurodegenerative disease characterized by loss of function and death of nerve cells in several areas of the brain leading to loss of cognitive function such as memory and language. "Additionally, DYNLRB2 plays a role in brain development and its deficiency is linked to Alzheimer’s disease." (PMID 40432967, 2025).
Hypercholesterolemia (1 paper, 2025). An increased concentration of cholesterol in the blood. "Mutations in DYNLRB2 have been associated with intraductal carcinoma of the breast, hypercholesterolemia, Jeune syndrome, short rib polydactyly type III, asphyxiating thoracic dystrophy, and abnormal cranial development in embryonic infants." (PMID 40432967, 2025).
oligospermia (1 paper, 2017). Decreased number of spermatozoa in the semen. "Eight genes among 817 genes (0.01%) (ADAM32, DYNLRB2, KLHL10, RIMBP3C, SEPT12, TIMD4, TSACC and TTC25) were common between MArrest and teratospermia, and three genes among 435 genes (0.007%) (HRASLS, LIMS3 and MRPL42) were common between oligospermia and teratospermia." (PMID 29150651, 2017).
tuberculosis (1 paper, 2013). A chronic, recurrent infection caused by the bacterium Mycobacterium tuberculosis. "For example, DYNLRB2 is involved in immune signaling and genetic variation in this gene is associated with tuberculosis susceptibility." (PMID 23509613, 2013).
tumor (2 papers, 2013 to 2023). "To further study the role of differentially expressed lncRNAs in tumor, we discovered through GO enrichment analysis that most differentially expressed lncRNAs were related to microtubule movement, including DYNLRB2, CFAP91, and ZMYND10." (PMID 37224123, 2023). "Additionally, a set of genes, including AFM, DYNLRB2, FDX1, and SHBG, were significantly downregulated in HCC-R tumor tissues with fold changes ≥4 involved in various small molecule biochemistry and molecular transport mechanisms." (PMID 24377043, 2013).
infection (1 paper, 2020). The state of being infected such as from the introduction of a foreign agent such as serum, vaccine, antigenic substance or organism. "On the other hand, over-expression of the DYNLRB2 levels had an enhancing effect over MLV infection, showing a functional role for DYNLRB2 on the MLV infection process." (PMID 32344581, 2020).
DYNLRB2 also shares sentences with these, for which no sentence is quoted: Cholestatic liver disease (1 paper); gallstones (1); Infertility (1); Insulin resistance (1); intraductal carcinoma of the breast (1); Jeune syndrome (1); teratospermia (1); type 2 diabetes (1).